CD4 (CD4 molecule)
Diseases named in the same sentence as CD4 in open-access papers (continued):
Sharing a sentence is not in itself a finding about the gene and the disease.
cancer (continued). "The immune response elicited by this DC-based cancer vaccine strategy includes the direct activation of TAA-specific CD4+ and CD8+ T cells in conjunction with indirect activation of innate immune cells, namely natural killer (NK) cells, NK T cells, and macrophages." (PMID 37580614, 2023). "As these results did not all distinguish different CD4 T cell subsets, it remains at present impossible to determine whether the prognostic value of CD4+ TILs is dependent on cancer type or heterogeneity in CD4 subsets, or both." (PMID 36564565, 2023). "Furthermore, the expression of SLC2A10 was significantly correlated with the infiltration levels of DCs in 19 types of cancers, neutrophils in 16 types of cancers, CD8+ T cells in 13 types of cancers, and CD4+ T cells and B cells in 11 types of cancers." (PMID 36873535, 2023). "LAYN is a key gene in the regulation of immunity, and a bioinformatics analysis showed that LAYN is associated with prognosis and the level of immune infiltration of CD8+ T cells, CD4+ T cells, macrophages, neutrophils, and DCs in patients with several cancers, especially colon and gastric cancers." (PMID 37901223, 2023). "CD4+ T-cell help for CD8+ T cells is crucial in the generation of robust effector and memory CTL responses: immunologic protection of CIITA transfected cells is due to the generation of primed CD4+ T cells providing help for the generation of cancer antigen-specific CTL effectors." (PMID 37565053, 2023). "Univariate Cox regression displays that B cells naïve, T cell CD4 memory resting, NK cells resting, Mast cells activated, and Neutrophils are prognosis-related factors in pan-cancer, in which forth three are protective factors while later four are risky factors." (PMID 37950731, 2023). "Interestingly GZMB+ and GZMK+ CD4s seem to be a part of distinct populations of cytotoxic CD4 T cells in human cancer patients." (PMID 37654482, 2023). "CD4+ T‐cell subsets with different functions are found in a wide range of cancers." (PMID 37313656, 2023). "Furthermore, the TCM-CXCL13+ subset represented an activated subset that had been presented antigens by antigen-presenting cells and potentially differentiated into the CD4+ CTL subset upon continuous exposure to antigens from cancer cells." (PMID 38077321, 2023). "Indeed, in cancer PD-L1 activation on T cells weakens antitumor immunity, while PD-L1 signaling on human memory CD4+ T cells induces a regulatory phenotype." (PMID 37920474, 2023). "CD4+ T cells could regulate anti-cancer immunity either directly by eliminating malignant cells or indirectly by activating innate immune cells." (PMID 36769082, 2023). "The results of the correlation analysis were visualized using a lollipop plot, which showed that the IRPM risk score was inversely correlated with the infiltration of multiple anti-cancer active ingredients, including CD4+T cells, B cells, NK cells, CD8+T cells, and DCs." (PMID 38203311, 2023). "In addition to their significance in these diseases, the increased focus on CD4+ T cells and CD4+ CTLs in cancer research has come about because only a minority of tumors respond to current immunotherapies including immune checkpoint inhibitor therapy." (PMID 38077321, 2023). "We observed that approximately 1–5% of CD4+ T cells from the blood of people living with HIV-1 exhibit over-duplicated centrioles, suggesting that centrosome amplification underlies the development of HIV-1-associated cancers by driving aneuploidy." (PMID 37645926, 2023). "CD4 + T cell epitope has been related to the protection against infections and cancer." (PMID 38046065, 2023). "CD4 T cells recognize antigens presented by HLA class II (HLA-II), which are traditionally expressed by APCs, but are increasingly detected in a variety of cancer cells." (PMID 37185301, 2023).
cancer (continued). "The relative proportion of CD4+ cells in the epithelial component versus the mesenchymal component was also increased in the NF-κB high group, consistent with the correlation being specific to the regions of epithelial (cancer) cells." (PMID 37523561, 2023). "The ABI3BP expression was significantly correlated with the abundance of infiltrating immune cells: B cells in seven cancers, NK cells in seven cancers, Mast cells in six cancers, Macrophage M2 cells in six cancers, and T cell CD4+ memory resting in six cancers." (PMID 37197424, 2023). "Therefore, the evaluation of CD4 T-cells senescence appears as a potential biomarker of a high serological response to the SARS-CoV-2 vaccine in the younger cancer patient population." (PMID 37334387, 2023). "Thus, a thorough understanding of immune responses to cancer must encompass immune cells (CD4 + T cells, CD8 + T cells, MDSCs and Tregs) across the peripheral immune system in addition to within the TME." (PMID 36853330, 2023). "However, in some cases, cells of epithelial lineage can express MHC II in response to interferon signalling and cytotoxic CD4+ T cells can kill MHC II+ cancer cells." (PMID 37386922, 2023). "The aim of the TERTIO study is to determine the clinical interest and immunological efficacy of a treatment combining the CD4 helper T-inducer cancer anti-telomerase vaccine (UCPVax) with atezolizumab and bevacizumab in unresectable HCC in a multicenter randomized phase II study." (PMID 37516867, 2023). "CD4+ T cell–B cell interaction relies on CD40–CD40L costimulatory signals, which mediate the generation of memory B cells and the formation of the GC,199, 200 which is positively associated with a favorable prognosis for a variety of cancers." (PMID 37829505, 2023). "The role of CD4+ T cells in cancer was thought to be primarily in priming immune response for CTLs." (PMID 36915911, 2023). "And we could observe a positive correlation between T cell CD4 and 22 cancer types, with the highest correlation being with KIRC (cor = 0.58, p < 0.0001)." (PMID 37371463, 2023). "We suggest that when malignancies weaken the body's immunity through different immunosuppressive pathways, the CD4+ T-lymphocyte content may decrease as the body's immune function is weakened." (PMID 37206348, 2023). "Aggressive CD4+/CD4+/CD8+ MF was more prevalent than CD3+/CD4+/CD8- MF cancer cases." (PMID 37829962, 2023). "Recent studies have identified genetic signatures of cytotoxic CD4+ TILs in some human cancers." (PMID 36512410, 2023). "To explore whether HIV-1 can induce centrosome abnormalities, we performed immunostaining analyses with CD4+ T cells purified from the PBMCs of five individuals living with HIV-1 (before they developed HIV-1-associated disorders, including cancer)." (PMID 37645926, 2023). "The relationship between SERPINE family genes expression and specific immune cells infiltration in human cancers, such as B cells, dendritic cells (DCs), CD4+ and CD8+ T cells, mast cells, neutrophils, natural killer (NK) cells, and macrophages, were identified." (PMID 38274096, 2023). "For these cell clusters with significant differences, Cluster 12 was annotated as endothelial cells, Cluster 13 was annotated as fibroblasts, Cluster 14 was annotated as cancer cells, Cluster 16 was annotated as myeloid cells and Cluster 18 was annotated as CD4 T cells." (PMID 36814498, 2023). "Immune checkpoint inhibitors (ICIs) act specifically to block CTLA4 and PD-1, so we compared GzmA and GzmB expression in CD57+ CD4+ T cells in blood obtained from cancer patients before and after treatment with anti-CTLA4/PD-1 (ipilimumab/nivolumab) combination checkpoint inhibitor therapy." (PMID 37161048, 2023). "Hence, using mIF, we identified CD8+ T-cell functional subsets and other cell populations in the TME, including cancer cells, CD4+ T cells, endothelial cell of cancer microvessels and cancer-associated fibroblasts." (PMID 37173705, 2023).
cancer (continued). "However, they can also develop potent granzyme (Gzm)-mediated cytotoxic activity and CD4+ cytotoxic T cells (CTLs) have been amply documented both in humans and in mice, particularly in the context of human chronic infection and cancer." (PMID 37122720, 2023). "A similar effect was observed using primary CD4+ T cells transduced with cancer-targeting TCRs." (PMID 37390984, 2023). "Although CD8 T cell exhaustion has been well-established and considered a target of immunotherapy for cancer patients, relatively few studies have focused on the importance of PD-1 blockade for increased PD-1 expression and the functional recovery of CD4 T cells." (PMID 37147330, 2023). "Moreover, in almost all cancer species, the KIFscore was positively correlated with T cell CD4+ TH2, the common lymphoid pro-genitor, and the T cell follicular helper." (PMID 37711200, 2023). "To this end, we selected cancer types with at least 10,000 CD4+ T cells for pan-cancer analyses." (PMID 36049666, 2023). "In this regard, we posit that CD4+CD26high T cells could be a biomarker in cancer management that may be used for the prevention, diagnosis, and selection of therapeutic methods and treatment monitoring of patients in the future." (PMID 37170241, 2023). "At several steps in this process, perturbations in CD4+ T-cell-epithelial interactions may influence cancer initiation and progression." (PMID 37654482, 2023). "In cancer patients, the balanced ratio of CD4+/CD8+ T cells throughout life might be another indicator for impaired capacity of immune response." (PMID 38102684, 2023). "Previous studies have reported that CD4+ T memory resting cells may be activated upon external stimuli and exert anti-cancer activity via activating CD8+ T cytotoxic cells." (PMID 36611966, 2022). "A more complete understanding of the signals and circuits regulating Eomes expression may thus provide broader strategies to modulate CD4 T cell responses to overcome dysfunctional cellular immunity in settings like chronic infectious disease and cancer." (PMID 36358898, 2022). "Furthermore, ILK was significantly correlated with B cells and CD8+ T cells in 10 cancers, with CD4+ T cells in 24 cancers, with macrophages and neutrophils in 23 cancers, and with DCs in 28 cancers." (PMID 35692780, 2022). "In addition, NETs facilitate naïve CD4+ T cells metabolic reprogramming, resulting in a positive correlation with the number of regulatory T cells (Tregs) in cancer." (PMID 36612251, 2022). "Interestingly, we observed that some immune cells have a relatively higher proportion in cancer, including T helper cells, naïve CD4 + T cells, exhausted CD8 + T cells, macrophages, B cells, plasma cells, and Treg cells." (PMID 36221095, 2022). "The results reveal that the expression levels of KRAS are significantly correlated with the infiltration levels of B cells, CD8+T cells, CD4+T cells, macrophages, neutrophils, and dendritic cells in 10, 13, 8, 9, 11, and 7 cancer types, respectively (correlation threshold ∣ R > 0.2, p < 0.05)." (PMID 35563733, 2022). "In conclusion, we demonstrated that, upon rhIL-15 stimulation, HODHBt could enhance the killing capacity of NK cells on HIV-infected CD4 T cells and different cancer cell models." (PMID 35867565, 2022). "Infiltrating levels of cancer-associated fibroblasts (CAF) and macrophages were elevated in high SERPINH1 expression samples, whereas infiltrating levels of B cells, CD4+ T cells, and CD8+ T cells were downregulated in high SERPINH1 expression samples compared to low SERPINH1 expression samples." (PMID 36104825, 2022). "It was documented that the type of infiltrates made of inflammatory, innate immune cells and CD4+ T-lymphocyte, may predict cancer progression." (PMID 35565367, 2022). "This might seem counterintuitive because PD-1+ CD8 and CD4 T cells in blood or in cancer are usually considered to be exhausted." (PMID 35661814, 2022).
cancer (continued). "Th1, Th2, and Th17 are subgroups of CD4+ T cells, which play an important role in immunoregulation, and natural killer cells are powerful effectors of innate immunity that constitute a first line of defense against cancer as well." (PMID 35950033, 2022). "Consequently, CD4+ T-cells and dnT-cells can be defined as a malignant tumor within ATLL, based on transcriptomic characteristics and either type of CNV abnormalities." (PMID 35464471, 2022). "Serum carotenoids can not only reduce oxidative stress but also enhance the proliferation of CD4+T cells and the activity of natural killer cells and play a certain role in inhibiting the occurrence and development of malignant tumors by regulating some cell signal transduction pathways." (PMID 36606230, 2022). "In addition, studies have demonstrated the modulating effects of mTORC1/2 on diverse human cells such as CD4, CD8, Treg, tumor-associated macrophages TAM, cancer-associated fibroblasts CAF, endothelial cells, and MDSCs (myeloid-derived suppressor cells)." (PMID 36428613, 2022). "The clinical application of this novel platform as a preventive vaccine for cancer has revealed its potential for modulating the immune system through the signaling pathway of type I interferon-r, involved with CD4+ and CD8+ T cell lineage and Toll-like receptors." (PMID 36560626, 2022). "The decrease in CD4+ T-helper cells may lead to a suboptimal lymphocyte-mediated immune response to cancer cells." (PMID 35436305, 2022). "In cancer patient, the suppression effect in CD4+ T cell seems to be more significant." (PMID 36097003, 2022). "The abnormal expression of RMI2 is negatively correlated with immune cells and stromal cells in most types of cancer, and it is closely related to B cells, CD4 T cells, CD8 T cells, T cells follicular helper and other TILs and a variety of immune-related genes (ICP, MMRs, m6A)." (PMID 35552266, 2022). "The ratio between CD8 T cells, CD4 T cells, and macrophages were calculated in this study, but we found that only the ratio between CD4 T cells and naive CD4 T cells was negatively correlated with cancer patient survival across different cancer types, except DLBC." (PMID 35008400, 2022). "Most immune cells showed a positive correlation with risk scores, especially hematopoietic stem cells of XCELL, resting memory CD4+ T cells, activated mast cells, M2 macrophages of CIBERSORT-ABS, B cells of QUANTISEQ, and cancer-associated fibroblasts of MCPCOUNTER." (PMID 36313374, 2022). "CD161+CD4+ T cells could play an immunoregulatory role through cytokine production and were increased in cancer patients compared with healthy individuals." (PMID 35558087, 2022). "Additionally, SSTR2-high groups of most cancers had higher median central memory CD4 T cell scores, activated CD4 T cell scores, and effector memory CD4 T cell scores (96.15%, 80.77%, and 88.46%, respectively)." (PMID 35264912, 2022). "Alterations in the proportions of infiltrating macrophages, CD8+ T cells, fibroblasts, and CD4+ T cells, in TME are associated with clinical progression of cancer and may be prognostically significant in various cancers." (PMID 35242245, 2022). "Indeed, chronic inflammation and the accumulation of immunosuppressive factors at the metastatic stage can lead to functional alterations in CD4 T lymphocytes, which play a crucial role in the immune surveillance of cancers." (PMID 35546670, 2022). "The CD4 T cell contribution to anti-cancer immunity has been much less studied." (PMID 36362027, 2022). "These algorithms suggested that the infiltration levels of immune cells like CD4+ T cells, CD8+ T cells, NK cells, and macrophage cells, as well as some kinds of stromal cells such as endothelial cells and cancer-associated fibroblasts, were positively correlated with risk scores." (PMID 36035178, 2022). "Indeed, there is increasing experimental evidence demonstrating the importance of CD4 immunity for cancer immunotherapy." (PMID 36362027, 2022).
cancer (continued). "In the present study, we demonstrated that PAs have cytoprotective effects on normal human CD4+ T lymphocytes but not on Jurkat or K562 cancer cells, and such protection is associated with the induction of the alternative splicing of RAD51 pre-mRNA." (PMID 35163785, 2022). "Actually, researchers reported the cytolytic CD4+ T cells mediated immunity against cancer." (PMID 35534879, 2022). "Furthermore, COL11A1 negatively correlated with B cells, CD4 and CD8 cells, but positively associated with cancer-associated fibroblasts." (PMID 36389832, 2022). "Immunocorrelation analysis showed Myeloid dendritic cell activated, T cell CD4+ naive, T cell CD8+, T cell CD8+ central memory, Common lymphoid progenitor, Myeloid dendritic cell, Endothelial cell, Cancer associated fibroblast, Macrophage M2, B cell memory were significantly related to risk score." (PMID 36035166, 2022). "Cancer incidence increased with age and decreased with higher CD4 cell counts at ART initiation." (PMID 34873875, 2022). "Indeed, a prognostic role for cancer-infiltrating CD4+ T cells with a regulatory T (Treg) cell phenotype has been described." (PMID 35158758, 2022). "This activation is distinct from the CD4+ T-cell-mediated humoral immunity to cancer-derived antigens, a typical mechanism of PLE; however, it may cause clinical symptoms similar to those of PLE, such as memory loss, and emotional and behavioral changes." (PMID 35736871, 2022). "In cancer cells, CD4+ lymphocyte infiltration orchestrates the immune response to cancer." (PMID 36568391, 2022). "In addition to activating CTLs, cancer vaccines have also investigated the role of CD4+ T helper cells." (PMID 35529885, 2022). "When cancer developed further, the proportion of CD4 + T cells increased significantly." (PMID 36185274, 2022). "Moreover, SPP1 expression was significantly related with the levels of infiltrating CD8 + cells, CD4 + cells, macrophages, neutrophils and dendritic cells in different types of cancers." (PMID 36585688, 2022). "The low infiltration of CD8 T cells and the high infiltration of memory-activated CD4 T cells in type B GC cancer may increase the efficacy of immune checkpoint inhibitor therapy in GC patients." (PMID 35965524, 2022). "It has been reported that acupuncture increases the levels of CD3+ and CD4+ and the CD4+/CD8+ ratio in the peripheral blood of patients with malignant tumors, highlighting the therapeutic effect of acupuncture by enhancing the cellular immune function of the patients." (PMID 35178106, 2022). "In cancer tissues, however, the abundance of different CD4 T cell subsets in TLSs is largely unknown." (PMID 36077836, 2022). "Besides, the frequencies of CD4+ Tn and CD8+ Tn decreased obviously and were associated with the development of cancer." (PMID 36119064, 2022). "We showed that the identified pathway activity profiles can be of help in elucidating the mechanism leading to cancer-induced immunotolerance and to investigate the type and the functional state of CD4+ T cells in blood, lymph nodes, and TIL samples from cancer patients." (PMID 35158758, 2022). "However, a fully effective cancer therapy must elicit a diverse repertoire of both CD4+ and CD8+ T cell responses, raising demands on a multifaceted activation of the MHC system." (PMID 35547749, 2022). "We speculated that Treg cells may also be converted from naïve CD4 + T cells in cancer and thus, we performed a trajectory analysis." (PMID 36221095, 2022). "Furthermore, anti-inflammatory cytokine IL-10 can inhibit anti-cancer response by shifting CD4+ pattern to T regular pattern and promote Treg generation." (PMID 36417428, 2022).